CD38 (CD38 molecule)
Diseases named in the same sentence as CD38 in open-access papers (continued):
Sharing a sentence is not in itself a finding about the gene and the disease.
acute promyelocytic leukemia (13 papers, 2016 to 2024). An aggressive form of acute myeloid leukemia (AML), characterized by arrest of leukocyte differentiation at the promyelocyte stage, due to a specific chromosomal translocation t(15;17) in myeloid cells. "ATRA is a potent and highly specific inducer of CD38 expression in human promyelocytic leukemia cells." (PMID 39296977, 2024). "We reported that all-trans retinoic acid (ATRA) is a potent and highly specific inducer of CD38 expression in human promyelocytic leukemia cells." (PMID 33096610, 2020). "Furthermore, RT-PCR also detected CCDC103 expression in human myeloid cells and myeloid progenitors, whole-blood-derived CD34+/CD38− cells, whole cord blood and in the promyelocytic leukemia HL-60 cell line." (PMID 34028558, 2021). "Further, regulation of its expression appeared to be dependent on a variety of factors, including exposure to all-trans retinoic acid (ATRA), a potent and highly specific inducer of CD38 expression in human promyelocytic leukemia cells that are now approved for in vivo use." (PMID 33096610, 2020). "Based on this, All-trans retinoic acid (ATRA) as a therapeutic factor of acute promyelocytic leukemia (APL) treatment has the ability to inducing CD38 expression on AML cells." (PMID 34412685, 2021). "Moreover, the treatment with all-trans retinoic acid (ATRA), clinically used for acute promyelocytic leukemia (APL), can induce CD38 upregulation in CD38low adult T-cell leukemia (ATL) cells, making them susceptible to CD38 CAR-T cells." (PMID 36624522, 2023). "Kikushige and Miyamoto reported that TIM-3 expression increased in CD34+/CD38- LSCs and blast cells in most AML patients, except for acute promyelocytic leukemia (M3), normal HSCs, and normal progenitors." (PMID 27506934, 2016). "TIM-3 has been identified as a marker of LSCs with lack of expression on normal CD34+CD38- HSCs but not CD34+CD38- LSCs in most types of AML except for acute promyelocytic leukemia (M3)." (PMID 36605213, 2022). "CD38 upregulation can be induced in CD38low adult T-cell leukemia (ATL) cells by treatment with all-trans retinoic acid (ATRA), a clinically accepted compound used to treat patients with acute promyelocytic leukemia (APL), thus exposing leukemic cells to recognition by CD38 CAR T cells." (PMID 33081391, 2020). "Originally, L-IC have been identified as CD34+CD38− cells (i.e., by the combination of CD34 expression and the lack of CD38 and other markers of advanced commitment) in most samples of AML patients but with the notable exception of patients suffering from acute promyelocytic leukemia (APL)." (PMID 26880987, 2016).
autism (13 papers, 2011 to 2023). Persistent deficits in social interaction and communication and interaction as well as a markedly restricted repertoire of activity and interest as well as repetitive patterns of behavior. "Expression of CD38 [and single nucleotide polymorphisms (SNPs) in the CD157 gene as a paralog of CD38] is correlated with scores on the Autism Quotient." (PMID 30210321, 2018). "In individuals with ASD, two SNPs of CD38 (rs6449197 and rs3796863) have been associated with high-functioning autism in the US population." (PMID 28283809, 2017). "Recently, accumulating evidence has suggested that single nucleotide polymorphisms in OT, OT receptors, and CD38 genes are associated with autism or high-functioning autism, or they are at least a risk factor." (PMID 27499729, 2016). "Previously, we found that CD157 and CD38 and their signaling pathways are shared in anxiety, autism, early atypical motor function, speech and language disorders, and social avoidance." (PMID 28566999, 2017). "The difference in CD38 positive(CD38p) B cell number in autism tracked with the increase in total B cellpopulation." (PMID 21573236, 2011). "Partial deletion of CD38 has also been reported in a patient with autism and asthma." (PMID 28283809, 2017). "CD38, a transmembrane glycoprotein involved in immune response, has been demonstrated to mediate abnormal oxytocin secretion, maternal nurturing, and social behavior in autism." (PMID 25895500, 2015). "The relationship between autism and a variation in the CD38 gene has been reported." (PMID 23874274, 2013). "In addition,there were significant differences in activated B cell subsets, includingstatistically significant increases in B cells that expressed the activationmarker CD38 in autism compared with controls (394.7±119.9 vs.479.7±210.2, p = 0.0081)." (PMID 21573236, 2011). "Microglia and CD38 may possibly play crucial roles in the pathophysiology and treatment of autism." (PMID 23874274, 2013). "CD38 and acid-related orphan receptor alpha (RORA) mRNA levels were used to assess autism-related biochemical indicators’ changes." (PMID 28938872, 2017). "The SNP rs3796863 (C > A) of the CD38 gene was associated with high-functioning autism (HFA) in both samples from the Autism Gene Resource Exchange and those from low-functioning autism subjects in Israel, but not in Japanese HFA subjects." (PMID 26010484, 2015). "In addition, increasedmarkers of cellular activation, such as CD38 on B cells, and HLA-DR and CD26 on Tcell subsets, were observed on cells from autism participants compared withcontrols." (PMID 21573236, 2011). "An in vitro study also demonstrated that RA can upregulate CD38 transcription levels; RA may regulate RORs (including RORA, RORB, RORR) through its retinoic acid receptors, which demonstrated the potential role of VA in autism biomarker." (PMID 28938872, 2017).
autism spectrum disorder (13 papers, 2012 to 2025). A spectrum of developmental disorders that includes autism, and Asperger syndrome. "Evidence for the associations of CD38 with social behavior and psychiatric disorder is discussed, especially in subjects with autism spectrum disorder." (PMID 26586001, 2016). "CD38−/− mice showed deficits in parental and social behaviors and furthermore, CD38 mutations have been associated with human autism spectrum disorder (ASD)." (PMID 26856703, 2016). "One review provided evidence from human and other animal studies that decreased VA is related to a variety of biological functions associated with autism spectrum disorder: low VA, and its hormone metabolite retinoic acid, led to decreases in CD38 and resulting decreases in oxytocin." (PMID 32999954, 2020). "CD38 genetic variation has been associated with autism spectrum disorders and social anxiety disorder, which may result from CD38’s regulation of oxytocin secretion." (PMID 32116489, 2020). "In the brain, Cd38 regulates the secretion of the neuropeptide oxytocin and is associated with several stress-related phenotypes, including social impairments in humans such as autism spectrum disorder." (PMID 29529077, 2018). "Finally, we focus on both single nucleotide polymorphisms (SNPs) of the human CD38 gene in relation to autism spectrum disorders (ASDs) and repetitive treatment of ASD patients with nasal administration of OXT." (PMID 23335873, 2012). "We found a significant positive causal relationship between 13 immune cells and autism spectrum disorder (ASD), including six CD8+ T cells, one CD3+ T cell, two CD20+ B cells, one CD38+ B cell, and two plasmacytoid DC." (PMID 40229469, 2025). "The aim of the present study was to analyze gene expression levels for oxytocin and vasopressin receptors, as well as CD38 protein and oxytocinase, in the context of the clinical picture of autism spectrum disorders." (PMID 37886970, 2023). "Diminished CD38 action figures in autism-spectrum disorders and CD38 knockout mice show impaired object- and social-recognition memory." (PMID 36012194, 2022). "Single-nucleotide polymorphisms of the CD38 and CD157/BST1 genes are associated with multiple neurological and psychiatric conditions, including autism spectrum disorder, Parkinson’s disease, and schizophrenia." (PMID 31881755, 2019). "Studies have shown that CD38−/− mice display autism spectrum disorder (ASD)-like behavioral phenotypes that can be reversed with OXT treatment and mutations in CD38 are associated with ASD in human patients." (PMID 26856703, 2016). "Importantly, CD38 mutations are associated with autism spectrum disorders (ASD) and CD38 knockout (CD38−/−) mice display ASD-like behavioral phenotypes including deficient parental behavior and poor social recognition memory." (PMID 26856703, 2016). "In this article, we mainly mention various characteristics of CD38 and CD157 in relation to brain function, behavior, and impaired behavior in KO mice which resemble the developmental disorders such as autism spectrum disorder (ASD)." (PMID 31881755, 2019).
cervical cancer (13 papers, 2020 to 2025). A primary or metastatic malignant neoplasm involving the cervix. "In cervical cancer, CD38 has been linked to increased proliferation, inhibition of apoptosis and PI3K/AKT/mTOR signaling activation." (PMID 34830895, 2021). "However, CD20 on IgD+ CD38+ B cell (OR=1.887, 95%CI:1.078-3.306, P=0.026) had a significant association with the probability of cervical cancer." (PMID 38746677, 2024). "The expression of CD38 RNA and protein was higher in cervical cancer tissues compared to normal tissues." (PMID 40382743, 2025). "On the other hand, high expression of CD38 promotes cervical cancer cell proliferation, and CD38 significantly enhances tumor growth in nude mice." (PMID 38545257, 2024). "Cell cycle analysis reveals that CD38 induces cell accumulation in the S phase and inhibits apoptosis in cervical cancer cells." (PMID 38545257, 2024). "In cervical cancer, CD38 enhances phosphorylation of PI3K, AKT and mechanistic target of rapamycin (mTOR), all crucial for cell survival and proliferation, mediated by its NADase activity impacting NAD levels and cellular metabolism." (PMID 39364393, 2024). "In tumor cells, CD38 had been shown to facilitate tumor proliferation and migration in lung and cervical cancer." (PMID 38463232, 2024). "Studies demonstrate that CD38 promotes cervical cancer cell growth by inhibiting apoptosis and reducing ROS levels." (PMID 36556252, 2022). "CD8+ MAIT cells displayed higher expression levels of the activation marker CD38 in cervical cancer patients versus healthy donors." (PMID 33808058, 2021). "Since CD38 was found to promote cell proliferation in cervical cancer, it is suggested that cell proliferation is due to abnormally expressed CD38." (PMID 34211854, 2021). "In our previously reported cervical cancer study 29, high expression of CD38 could induce cell cycle changes in cervical cancer cells and promote cell cycle arrest in the G1/S phase." (PMID 36605482, 2023). "However, with more research expanding the field, CD38 has been confirmed as expressed in multiple types of solid tumors such as nasopharyngeal cancer, cervical cancer, and skin cutaneous melanoma." (PMID 34211854, 2021). "Interestingly, CD38 activates the PI3K/AKT/mTOR signaling in cervical cancer cells." (PMID 36490326, 2022). "In cervical cancer cells, CD38 could promote cell proliferation and inhibit cell apoptosis." (PMID 34211854, 2021).
colorectal cancer (13 papers, 2020 to 2026). A primary or metastatic malignant neoplasm that affects the colon or rectum. "CD38+ NK cell proportions in the peripheral blood and tumor tissues are also increased in patients with colorectal cancer (CRC)." (PMID 42292426, 2026). "According to our study, colorectal cancer patients have a much greater CD38 + NK cell proportion in the peripheral blood." (PMID 41530841, 2026). "In the same study the percentage of CD24 high CD38 high (transitional) B cells was lower in tumor samples than in peripheral blood of colorectal cancer patients and transitional B cells were very rare in early-stage CRC (p < 0.05)." (PMID 41008839, 2025). "These CD38+ M-MDSCs possessed a greater capacity to suppress the T cell proliferation by a mixed lymphocyte reaction assay, which contributed to colorectal cancer (CRC) pathogenesis." (PMID 34211854, 2021). "CD38 expression in colorectal cancer was enhanced on monocytic myeloid-derived suppressor cells (M-MDSCs)." (PMID 34211854, 2021). "Colorectal cancer patients had a higher proportion of CD8+CD38+ T cells than healthy controls." (PMID 36307548, 2022). "BAFF-R on IgD+ CD38− naive B cell (ebi-aGCST90001706; IVW: OR [95%CI] = 1.034 [1.007–1.061], P = .012), etc, 11 immune cell attributes correlated with colorectal cancer." (PMID 39612465, 2024). "The expression of CD38 is related to immunosuppressive macrophages in patients with renal clear cell carcinoma and MDSC-mediated T cell suppression in colorectal cancer." (PMID 35725444, 2022). "Also, in the same study CD27+IgD− memory B cells were elevated in colorectal cancer tumor compared to peripheral blood of healthy controls (p < 0.005) and IgD+/CD27−/CD38− B cells are decreased in tumor samples of colorectal cancer patients." (PMID 41008839, 2025). "A significant expansion of CD38+ monocytic and polymorphonuclear myeloid-derived suppressor cells (M-MDSCs and PMN-MDSCs) with a tendency to increase CD38 expression on M- and PMN-MDSCs can be observed in peripheral blood mononuclear cells of patients with colorectal cancer (CRC)." (PMID 36077708, 2022).
mantle cell lymphoma (13 papers, 2015 to 2024). Mantle cell lymphoma is a rare form of malignant non-Hodgkin lymphoma affecting B lymphocytes in the lymph nodes in a region called the ``mantle zone''. "CD38 is another surface marker that is overexpressed in several types of tumors, such as mantle cell lymphoma (MCL) and multiple myeloma (MM)." (PMID 38516300, 2023). "CD38 is also expressed on malignant cells from B-CLL, mantle cell lymphoma (MCL), transformed FL, and clinical trials are ongoing with daratumumab in these diseases." (PMID 26425544, 2015).
Stroke (13 papers, 2011 to 2025). Sudden impairment of blood flow to a part of the brain due to occlusion or rupture of an artery to the brain. "CD38 is differentially regulated following stroke and its deficiency attenuates the postischemic chemokine production, the immune cell infiltration and the cerebral injury after temporary ischemia and reperfusion." (PMID 21625615, 2011). "Of note, an increased expression of the Cd38 transcript in NAD+ deficient mice suggests that after stroke Cd38 mRNA could act in concert with the Gpd1 transcripts from astrocytes to increase glucose availability." (PMID 36818562, 2023). "Therefore, we investigated the dynamics of CD38 in stroke and the impact of CD38-deficiency on cytokine production, inflammation and cerebral damage in a mouse model of cerebral ischemia-reperfusion." (PMID 21625615, 2011). "After stroke, astrocytes were shown to secrete extracellular mitochondrial particles through cluster of differentiation 38 (CD38; also known as cyclic ADP ribose hydrolase)-dependent pathways, which were then taken up by neurons." (PMID 40149801, 2025). "CD38 is also involved in astrocyte-induced neuroprotection as it participated to the transfer of mitochondria from astrocytes to neurons after stroke." (PMID 37332353, 2023). "In experimental studies on models of stroke, glial cells transported mitochondria to neurons to protect the latter from hypoxia, and this process involved CD38 cells; the suppression of CD38 signaling worsened neurological outcomes." (PMID 34638589, 2021). "CD38 is also involved in the transfer of mitochondria from astrocytes to neurons after stroke, thus linking CD38 to astrocyte-induced neuroprotection." (PMID 32085567, 2020). "Our data show that these processes highly depend on CD38, because macrophages strongly up-regulate CD38 upon stroke and highly rely on CD38 for effective migration into the ischemic brain." (PMID 21625615, 2011). "Additionally, an elevated susceptibility to stroke was linked to an increase in the percentage of CD39+ resting Tregs and heightened CD27 expression on IgD- CD38+ cells." (PMID 38887301, 2024). "Furthermore, an increase in Cd38 mRNA in perivascular macrophages has been also noted in response to ischemic stroke in stroke patients and in a mouse model of stroke." (PMID 36818562, 2023). "Relevant studies have shown that astrocytes may release MVs mitochondrial particles via CD38-mediated mechanisms that enter neurons after stroke." (PMID 36927781, 2023). "Astrocytes promote the survival of neurons by producing mitochondrial EVs after a stroke, while the inhibition of CD38 was shown to significantly decrease the number of mitochondria containing EVs, suggesting that a CD38-dependent pathway is required for the ejection of these EVs." (PMID 36551198, 2022). "We have shown that CD38 orchestrates the recruitment and activation of immune cell subpopulations, the production of pro-inflammatory cytokines and cytotoxic autoimmune response after stroke." (PMID 21625615, 2011). "Therefore macrophages could be the key player to orchestrate the CD38-dependent effects, because they represent one of the earliest cell populations to infiltrate the ischemic brain, up-regulate CD38 after stroke and are known to be a major source of MCP-1 production." (PMID 21625615, 2011). "With IHC, we found CD20+ B cells, CD138+ plasma cells, and IgG+ plasmablasts in close proximity to microglia nodules in MS and not in stroke, and in MS more microglia nodules were associated with activated, proliferating CD3+ T cells and CD38+ plasmablasts." (PMID 38396116, 2024).